LY6S-AS1 (LY6S antisense RNA 1)
Synonyms: FLJ37131; C8orf31; LINC02904
Gene: Long non-coding RNA gene on chromosome 8 (143,039,209 to 143,060,684, forward strand). Ensembl gene ENSG00000177335.
Diseases named in the same sentence as LY6S-AS1 in open-access papers:
LY6S-AS1 is named in the same sentence as 1 disease in open-access papers, as found by Europe PMC text mining. Sharing a sentence is not in itself a finding about the gene and the disease.
LY6S-AS1 shares sentences with these, for which no sentence is quoted: breast carcinoma (1 paper).